IL19 (interleukin 19)
Diseases named in the same sentence as IL19 in open-access papers (continued):
Sharing a sentence is not in itself a finding about the gene and the disease.
eosinophilia (2 papers, 2021 to 2025). "The top proteins with the largest log2 fold change in this group included IL-19, STAT5B, CCL17, S100A12, and CCL22—inflammatory mediators known to be associated with AD inflammation and eosinophilia." (PMID 41357518, 2025). "All immune constituents contributed to the model but some, identified by variable-important-in-projection values > 1 and p < 0.1, contributed more strongly, including BAL Th1 and Th2 cells and eosinophilia, CCL26 (Eotaxin 3), IgA and IL-19 concentrations in blood." (PMID 34349761, 2021).
esophageal cancer (2 papers, 2013 to 2025). A primary or metastatic malignant neoplasm involving the esophagus. "The findings of strong associations between IL-19 expression and several adverse clinicopathologic prognosticators suggested its crucial role in tumor progression of esophageal cancer." (PMID 24130695, 2013). "The present study provides evidence that IL-19 is associated with the pathogenesis of esophageal cancer." (PMID 24130695, 2013). "In particular, esophageal cancer cells express both IL-19 and its receptor IL-20R1/IL-20R2, suggesting a potential autocrine signaling loop." (PMID 40806452, 2025). "IL-19 directly influences esophageal cancer progression, inducing the expression of inflammatory mediators." (PMID 40806452, 2025). "This blockade led to reduced expression of IL-19-regulated genes such as TGF-β, Matrix Metalloproteinase-1 (MMP-1), CXCR4, and Cyclin B (CCNB1), highlighting the therapeutic potential of IL-19 inhibition in esophageal cancer." (PMID 40806452, 2025). "Intracellular signal transduction plays a role in esophageal cancer, we analyzed the effect of IL-19 on intracellular signaling in CE81T cells." (PMID 24130695, 2013). "IL-19 directly affected esophageal cancer cell proliferation and migration and promoted tumor progression." (PMID 24130695, 2013). "We demonstrate that IL-19 is an important local mediator in the microenvironment that affects esophageal cancer cells progression." (PMID 24130695, 2013). "We conclude that IL-19 has an autocrine effect and provides a microenvironment that affects tumor progression in esophageal cancer." (PMID 24130695, 2013). "Esophageal cancer cells expressed IL-19 receptors, which indicates that IL-19 is an autocrine factor in esophageal cancer." (PMID 24130695, 2013). "In this study, we investigated the effects of IL-19 in the pathogenesis of esophageal carcinoma in vitro and in vivo." (PMID 24130695, 2013). "We hypothesize that IL-19 augments cancer progression through its autocrine signaling, and that IL-19 may be the target for therapeutic in esophageal cancer." (PMID 24130695, 2013). "IL-19 mAb (1BB1) is potentially a potent drug for esophageal cancer therapy." (PMID 24130695, 2013). "Thus, we believe that IL-19 produced by esophageal cancer cells promotes tumor progression through its autocrine effect and by providing a microenvironment for tumor progression." (PMID 24130695, 2013). "IL-19 specifically modulated esophageal cancer cell proliferation via its receptors." (PMID 24130695, 2013). "To investigate the role of IL-19 in the pathogenesis of esophageal cancer, we first determined the expression of protein and mRNA of IL-19 and its receptors IL-20R1/IL-20R2 in esophageal cancer cell CE81T using immunocytochemical stains and RT-PCR, respectively." (PMID 24130695, 2013). "This might also be one of the mechanisms by which overexpression of IL-19 in esophageal cancer cells promotes tumor progression in vivo." (PMID 24130695, 2013). "Antagonizing IL-19 may have therapeutic potential in esophageal cancer." (PMID 24130695, 2013). "However, the role of IL-19 in esophageal cancer remains unclear." (PMID 24130695, 2013). "IL-19 is expressed in esophageal squamous cell carcinoma (SCC), but its biological effect on esophageal cancer remains unclear." (PMID 24130695, 2013).
esophageal squamous cell carcinoma (2 papers, 2013 to 2025). Esophageal squamous cell carcinoma (ESCC) is a type of esophageal carcinoma (EC) that can affect any part of the esophagus, but is usually located in the upper or middle third. "Of the 60 esophageal SCC patients, 36 patients (60%) were IL-19 strongly stained, which was associated with advanced tumor stage." (PMID 24130695, 2013). "IL-19 expression in esophageal SCC is associated with tumor metastasis and clinical stage." (PMID 24130695, 2013). "In vivo studies using an anti-IL-19 monoclonal antibody—which binds directly to IL-19 and prevents its interaction with the IL-20R1/IL-20R2 receptor complex—have demonstrated suppression of tumor growth in esophageal squamous cell carcinoma." (PMID 40806452, 2025). "Similar results have been obtained in the human esophageal SCC cell line, in which these effects were reversed by using a monoclonal antibody against IL-19." (PMID 40806452, 2025). "We determined the correlation between IL-19 expression levels and clinicopathological variables and explored the effects of IL-19 on the esophageal SCC in vivo and in vitro." (PMID 24130695, 2013). "We examined the effects of IL-19 on intracellular signaling, cytokines production as well as proliferation, colonization, and migration in the human esophageal SCC cell line CE81T." (PMID 24130695, 2013).
glioblastoma (2 papers, 2025). The most malignant astrocytic tumor (WHO grade IV). "Elevated levels of IL-19 have been associated with various cancers, including BC and glioblastoma multiforme (GBM)." (PMID 40806452, 2025). "Prussian blue staining further confirmed the localization of these nanoparticles in tumor tissues, verifying their potential as a diagnostic tool for detecting IL-19 expression in glioblastoma." (PMID 40057744, 2025). "For clinical translation, we developed a novel CHOL-PEG-SPIO-IL-19 nanoparticles to target IL-19 expression in glioblastoma tissue." (PMID 40057744, 2025).
invasive ductal carcinoma (2 papers, 2013 to 2023). "Studies have also shown that in invasive ductal carcinoma specimens, increased IL-19 expression correlates with high tumor metastasis, advanced tumor grade, and worse survival." (PMID 37675062, 2023). "Interleukin-19, a cytokine secreted by monocytes, in the interleukin-10 family, is expressed by several tumor cells which include invasive ductal carcinoma of the breast, squamous cell carcinoma (SCC) of the esophagus, tongue, lung, and skin." (PMID 37675062, 2023).
ischemia (2 papers, 2020 to 2021). A hypoperfusion of the BLOOD through an organ or tissue caused by a PATHOLOGIC CONSTRICTION or obstruction of its BLOOD VESSELS, or an absence of BLOOD CIRCULATION. "It should be noted that several other interleukins such as IL-19 and IL-21 also contribute to myocardial injury during ischemia, so we may need more investigation on them in the future." (PMID 32293300, 2020).
lung carcinoma (2 papers, 2022). "In this study, we show that the IL-19/IL-20RB axis mediates a direct osteoclastic stimulus to tumor to enhance the proliferation of disseminated lung cancer cells in bone and that IL-20RB can be targeted to treat lung cancer bone metastasis." (PMID 36006737, 2022). "Together, these data demonstrate that JAK1/STAT3 signaling is activated in IL20RB-expressing lung cancer cells by osteoclast-secreted IL-19." (PMID 36006737, 2022). "Taken together, these data suggest that tumor cells can induce the secretion of IL-19 from osteoclasts and that osteoclast-derived IL-19 in turn facilitates the proliferation of IL20RB-expressing lung cancer cells." (PMID 36006737, 2022). "Importantly, immunostaining of clinical bone metastases of lung cancer showed abundant expression of IL-20RB in tumor cells and IL-19 in microenvironmental cells." (PMID 36006737, 2022). "Thus, we tested to determine whether osteoclast-derived IL-19 activates STAT3 in lung cancer cells." (PMID 36006737, 2022).
lupus (2 papers, 2013 to 2025). "The gene cluster that includes interleukin 10 (IL10), IL19, IL20 and IL24 is located on chromosome 1q31-32, a genomic region that is linked with susceptibility to systemic lupus erythematosus (SLE, OMIM 152700)." (PMID 24130510, 2013).
multiple sclerosis (2 papers, 2021 to 2022). A progressive autoimmune disorder affecting the central nervous system resulting in demyelination. "Multiple sclerosis (MS) is a major neuroinflammatory disease in the central nervous system (CNS), but it remains uncertain how IL-19 contributes to MS pathogenesis." (PMID 33776998, 2021).
nasal polyp (2 papers, 2021 to 2022). "The IL-19 mRNA was significantly overexpressed in the nasal polyp group compared with that in both the CRSsNP and control groups." (PMID 36003393, 2022). "In conclusion, we demonstrated prominent expression of IL‐19 in nasal polyps of patients with CRSwNP, along with increased expression of tissue remodeling factor MMP‐9." (PMID 33900049, 2021).
neutropenia (2 papers, 2023 to 2024). A decrease in the number of neutrophils found in the blood. "mTORC1 activation enhances the production of IL-19 by osteocytes, and IL-19 has been proven to be a robust stimulation of granulopoieses, relieving chemotherapy- and irradiation-induced neutropenia even more effectively than G-CSF." (PMID 37223096, 2023).
osteoporosis (2 papers, 2024 to 2025). A condition of reduced bone mass, with decreased cortical thickness and a decrease in the number and size of the trabeculae of cancellous bone (but normal chemical composition), resulting in increased fracture incidence. "We demonstrated that the expression and secretion levels of IL-19 in mouse BMMs increased with age, and that BMMs-specific knockdown of IL-19 alleviated bone loss and osteoporosis in old mice." (PMID 38300634, 2024). "Upon conducting a heterogeneity assessment, IL-19 was excluded from subsequent analysis due to significant heterogeneity, while the remaining two factors, IL-18 and Artemin, demonstrated remarkable links with osteoporosis." (PMID 41329541, 2025). "Consequently, IL-19 emerges as a promising therapeutic target for the management of osteoporosis." (PMID 38300634, 2024). "Consequently, additional research is imperative to ascertain whether the involvement of IL-19 in age-related osteoporosis is connected to inflammatory mechanisms." (PMID 38300634, 2024).
palmoplantar pustulosis (2 papers, 2023 to 2025). A rare skin disease characterized by chronic eruption of sterile pustules on an erythematous and desquamative background, affecting the palms and soles, sometimes also the lateral aspects of hands and feet. "•Interleukin-19 may be a predictive biomarker for the therapy response in palmoplantar pustulosis." (PMID 39618912, 2025).
pernicious anemia (2 papers, 2022 to 2023). Megaloblastic anemia caused by vitamin B-12 deficiency due to impaired absorption. "A study on the cytokine profile of patients with pernicious anemia demonstrated a notable elevation in their serum IL-19 levels compared with healthy controls." (PMID 37504250, 2023). "Furthermore, an in vitro investigation of gastric lamina propria mononuclear cells derived from patients with pernicious anemia revealed their capacity to produce augmented levels of IL-19." (PMID 37504250, 2023).
pulmonary fibrosis (2 papers, 2022 to 2025). Chronic progressive interstitial lung disorder characterized by the replacement of the lung tissue by connective tissue, leading to progressive dyspnea, respiratory failure, or right heart failure. "It was found that the lung fibrosis tissues exhibited higher mRNA expressions of IL-19 compared with the normal lung tissues in both human and mice." (PMID 35281428, 2022). "KEGG functional enrichment analysis showed that TGF-β/Smad pathway enriched in human and mouse lung fibrosis and the expression of IL-19 in IPF was positively correlated with the profibrosis critical TGF-β/Smad signaling pathway." (PMID 35281428, 2022). "Overall, our study highlights the role of IL-19 on pulmonary fibrosis in vitro and vivo and proposes a new insight for future research and provides a promising management strategy for treating pulmonary fibrosis." (PMID 35281428, 2022). "Our results imply the profibrotic role for IL-19 through direct effects on lung fibroblasts and the potential of targeting IL-19 for therapeutic intervention in pulmonary fibrosis." (PMID 35281428, 2022). "IL-19 immunohistochemical staining revealed the higher IL-19 expressions in lung fibrosis tissues, as well as alpha smooth muscle Actin (α-SMA)." (PMID 35281428, 2022). "To determine the effect of IL-19 in progression of pulmonary fibrosis in vivo, we, respectively, administered a single dose of IL-19 (200 ng/kg) or BLM (2.5 mg/kg) or combination of these two treatments to wild-type C57BL/6 mice by intratracheal route." (PMID 35281428, 2022). "Here, we investigated IL-19 expression in human and mouse lung fibrosis tissues and the effect of IL-19 on lung fibroblasts as well as the possible mechanism." (PMID 35281428, 2022). "Additionally, elevated IL19 levels have been implicated in bone metastasis from LC and the progression of other respiratory diseases, such as COPD and pulmonary fibrosis." (PMID 40853920, 2025). "Consistently, our data support the mechanism of fibroblasts activation by IL-19 that lung fibroblasts are converted to MFs, implying that targeting at IL-19 may be a potential treatment strategy for lung fibrosis." (PMID 35281428, 2022). "Furthermore, we found that IL-19 aggravated lung fibrosis in murine bleomycin-induced lung fibrosis." (PMID 35281428, 2022). "Collectively, these studies demonstrated that IL-19 treatment could promote and aggravate the lung fibrosis progression induced by BLM in vivo." (PMID 35281428, 2022). "Whether epithelial cells could produce IL-19 to participate the progression and pathogenesis of lung fibrosis is worthy of further study." (PMID 35281428, 2022). "Then, we focused on role of IL-19 on wild-type mice and bleomycin(BLM)-induced pulmonary fibrosis mouse models." (PMID 35281428, 2022). "In vivo study, we determine that IL-19 aggravates lung fibrosis in wild-type mice and BLM-induced pulmonary fibrosis models." (PMID 35281428, 2022). "In conclusion, our study firstly highlights the deleterious role of IL-19 on development of pulmonary fibrosis by modulating fibroblasts through TGF-β/Smad pathway and reinforces its promise as a new therapeutic target for intervention in pulmonary fibrosis." (PMID 35281428, 2022). "However, none of studies explore the role of IL-19 in the etiopathogenesis of pulmonary fibrosis." (PMID 35281428, 2022).
pulmonary TB (2 papers, 2019 to 2023). "While the role of IL-20 cytokines in TB is poorly investigated, one report demonstrated that IL-19 and IL-24 are elevated in pulmonary TB patients and in vitro neutralization of these cytokines resulted in an enhanced CD4+ Th1/Th17 responses." (PMID 38162636, 2023). "Similarly, the increased expression of IL-19 and IL-24 in active pulmonary tuberculosis patients also mediated decreased expression of Th1/Tc1 and Th17/Tc17 cytokine in CD4+ and CD8+ T cells." (PMID 31921658, 2019).
squamous cell carcinoma (2 papers, 2012 to 2013). A carcinoma arising from squamous epithelial cells. "IL-19 is expressed in several types of tumor cells, especially in squamous cell carcinoma of the skin, tongue, esophagus, and lung and invasive duct carcinoma of the breast." (PMID 23710200, 2013). "IL-19 protein was positively stained in several types of tumor cells, especially in squamous cell carcinoma (SCC) of the skin, tongue, esophagus, and lung and invasive duct carcinoma (IDC) of the breast." (PMID 23710200, 2013). "Recent work demonstrated IL-19 expression in numerous neoplastic cell types, including cells of squamous cell carcinoma of the oral cavity, in which IL-19 promoted proliferation." (PMID 22844641, 2012).
tuberculosis (2 papers, 2013 to 2023). A chronic, recurrent infection caused by the bacterium Mycobacterium tuberculosis. "Whereas analysis of fold-induction showed significant induction of IL-19, IL-20, IL-24, and IL-26 by M. tuberculosis, the differences detected between the tuberculosis-IRIS and non-IRIS groups were neither great nor statistically significant." (PMID 23303806, 2013). "In PBMCs from both tuberculosis-IRIS and non-IRIS patients, M. tuberculosis stimulation resulted in increased transcript abundance for many of the cytokines, most prominently IL-19, IL-20, IL-24, and IL-26." (PMID 23303806, 2013).
uveitis (2 papers, 2021 to 2022). An inflammatory process affecting a part of or the entire uvea. "In particular the up regulation of IL19 gene, associated to non infectious uveitis and conjunctivitis could be related to SARS-CoV-2 infection in our patients." (PMID 34615949, 2021).
acute coronary syndrome (1 paper, 2023). Signs and symptoms related to acute ischemia of the myocardium secondary to coronary artery disease. "Nicorandil suppresses the inflammatory cytokines IL-1β, IL-1, IL-6, IL-10, IL-18, IL-19 and TNF-α in acute coronary syndrome patients." (PMID 34595611, 2023).
age (1 paper, 2024). A temporal measurement of the time period elapsed since an identifiable point in the life cycle of an organism. "In our study, we have pinpointed the role of IL-19 in age-related bone loss and its methylation-dependent regulatory mechanisms." (PMID 38300634, 2024). "High expression of IL-19 promotes osteoclast differentiation, which in turn induces bone loss in old mice, and participates in the onset and progression of age-related bone loss." (PMID 38300634, 2024). "IL-19, a cytokine exhibiting both pro-inflammatory and anti-inflammatory properties, plays a complex role in age-related bone loss, potentially involving a variety of inflammatory mediators and multiple biological pathways." (PMID 38300634, 2024).
allergic asthma (1 paper, 2019). A asthma with a basis in a pathological type I hypersensitivity reaction. "In this study, we investigated the role of IL-19 in asthmatic animal models in order to determine the therapeutic potential of IL-19-signaling antagonists for treating allergic asthma." (PMID 31114590, 2019). "We also found that IL-19 upregulated IL-13 and IgE production in asthmatic mice and that IL-19 induced Th2 cytokines in vitro, which suggested that IL-19 is substantially involved in allergic asthma." (PMID 31114590, 2019). "Our study suggests that targeting IL-19 signaling might be a novel therapeutic strategy for treating allergic asthma." (PMID 31114590, 2019). "Nevertheless, our data provided evidence that blocking IL-19 signaling may be a potential treatment strategy in these two commonly used preclinical rodent models of experimental allergic asthma." (PMID 31114590, 2019). "We next examined whether IL-19 is involved in the pathogenesis of HDM-induced allergic asthma." (PMID 31114590, 2019).